TMEM255B (transmembrane protein 255B)
Synonyms: FAM70B; MGC20579
Tractability: Antibody: UniProt predicts a signal peptide or a membrane-spanning region.
Gene: Protein-coding gene on chromosome 13 (113,759,194 to 113,816,995, forward strand). Ensembl gene ENSG00000184497.
Subcellular location: Membrane
Subcellular location (Human Protein Atlas): Nucleoplasm
Gene Ontology:
Molecular function: protein binding
Cellular component: membrane
Genetic constraint (gnomAD): Loss-of-function variants: 36 observed, 35.14 expected, observed/expected ratio (o/e) 1.02, 90% interval 0.78 to 1.35. The upper end of that interval is the gene's LOEUF score, 1.35, which puts it in group 5 of 6, group 1 being the genes least tolerant of losing a copy. Missense variants: 432 observed, 432.59 expected, observed/expected ratio (o/e) 1, 90% interval 0.92 to 1.08. Synonymous variants: 206 observed, 198.29 expected, observed/expected ratio (o/e) 1.04, 90% interval 0.93 to 1.17.
Homologues: Orthologues: macaque TMEM255B (95% identical), mouse Tmem255b (78% identical), pig TMEM255B (77% identical), guinea pig TMEM255B (77% identical), chimpanzee TMEM255B (74% identical), rat Tmem255b (73% identical), tropical clawed frog tmem255b (61% identical), zebrafish si:dkey-283j8.1 (33% identical).
Diseases named in the same sentence as TMEM255B in open-access papers:
TMEM255B is named in the same sentence as 4 diseases in open-access papers, as found by Europe PMC text mining. Sharing a sentence is not in itself a finding about the gene and the disease. The quoted sentences say what the papers report.
tumor (2 papers, 2018 to 2024). "However, the mechanisms by which GABRD and TMEM255B mediate tumor angiogenesis and proliferation remain to be elucidated." (PMID 38997406, 2024).
TMEM255B also shares sentences with these, for which no sentence is quoted: hepatic carcinomas (1 paper); pancreatic cancer (1); prostate carcinoma (1).